CXCR4 (C-X-C motif chemokine receptor 4)
Diseases named in the same sentence as CXCR4 in open-access papers (continued):
Sharing a sentence is not in itself a finding about the gene and the disease.
AIDS (continued). "Since the antagonists of CXCR4 are used to treat CXCR4-related diseases like AIDS and some cancers, it is reasonable to assume that the PPI molecule identified from the work should enhance their drug efficacies." (PMID 31787895, 2019). "Prediction of coreceptor tropism based on the env gp120 V3 region indicated that 50% (3 of 6) and 58% (7 of 12) of the participants had CXCR4-using viruses in the asymptomatic and AIDS stages, respectively (P = 1.00, two-tailed Fisher’s exact test)." (PMID 30333167, 2019). "In 2004, the Bond lab demonstrated that Nef interacts with CXCR4 to dispose of uninfected CD4+ T cells which likely contributes to AIDS progression in vivo." (PMID 29682200, 2018). "Most transmitting HIV-1 isolates as well as viral isolates recovered during the early stages of infection utilize CCR5, whereas a subset of isolates found at later stages of infection such as during the development of AIDS utilize CXCR4." (PMID 29677220, 2018). "It has been widely assumed that the switch in receptor usage from CCR5 to CXCR4 is a key event in progression to human AIDS." (PMID 29056666, 2017). "Together, this work represents a proof-of-principle study and provides a potential alternative approach for HIV-1/AIDS genetic therapy by targeting CXCR4 with AAV-deliver SaCas9/sgRNAs." (PMID 29141633, 2017). "For example, it will be interesting to further examine whether the increased levels of CXCR4 expression in the elderly is associated with an increased frequency of the CCR5 to CXCR4 co-receptor switch that is associated with rapid progression to AIDS in untreated HIV-1-infected individuals." (PMID 26452480, 2015). "The C-X-C chemokine receptor type 4 (CXCR4) acts as an important pro-inflammatory factor in the neuropathogenesis of HIV/AIDS." (PMID 25078297, 2014). "HIV, the etiological agent for AIDS, primarily infects T cells and macrophages by using CXCR4 and CCR5 as the primary coreceptors, respectively." (PMID 23509733, 2013). "HIV-1 preferentially uses CCR5 during the acute phase of infection but, later in the course of HIV-1 infection progressing to AIDS, HIV-1 variants frequently appear that become adapted to utilize CXCR4." (PMID 24312095, 2013). "Taken together, we have identified BSSL as a marker for HIV-1 progression to AIDS and the emergence of CXCR4-using viruses in HIV-1 infected MSM." (PMID 22412885, 2012). "While R5 viruses using CCR5 coreceptor were predominant at birth (94%) and at early AIDS (85%), viruses using CXCR4 coreceptor emerged during the course of infection and were detected in 49% of children older than 84 months and in 62% of late AIDS." (PMID 22962615, 2012). "Very recently, BSSL was identified as a marker for HIV-1 progression to AIDS and emergence of CXCR4-using viruses in HIV-1 infected patients." (PMID 23071697, 2012). "Coreceptor switching from early CCR5 usage to late CXCR4 usage in HIV infections is associated with rapid CD4 decline and AIDS development." (PMID 23202514, 2012). "The subsequent emergence of HIV variants that use the CXCR4 coreceptor in roughly half of all infections is associated with an accelerated decline of CD4+ T-cells and rate of progression to AIDS." (PMID 23133358, 2012). "In patients, the emergence of CXCR4-tropic virus usually occurs after years of infection and correlates with more rapid progression to AIDS." (PMID 22448282, 2012). "The association of additional chemokine receptors, beyond the primary CCR5 and CXCR4, with AIDS progression is plausible as several of these have been shown to bind to HIV in varying degrees." (PMID 22046140, 2011). "A change in coreceptor preference from CCR5 to CXCR4 late in infection has been well documented in some HIV-1 infected individuals since the early days of the AIDS epidemics, but the reasons and mechanisms for this tropism switch remain elusive." (PMID 21760891, 2011).
AIDS (continued). "Simulations show that adding a CXCR4 inhibitor with an efficacy of at least 5% is sufficient to prevent accelerated AIDS onset in the “competitive regime”." (PMID 19680436, 2009). "CXCR4 is a co-receptor for the T-trophic HIV seen in the late phase of HIV infection associated with a more rapid deterioration of the immune system and faster progression to AIDS." (PMID 40075611, 2025). "Also, there is higher CXCR4 expression in HIV as CXCR-4 also serves as a co-receptor for HIV entry into CD4+ cells and is associated with more rapid immunosuppression and faster progression to AIDS." (PMID 39001265, 2024). "Moreover, MSM with AIDS can experience a transformation of the co-receptor from C–C motif chemokine receptor 5 (CCR5) to C-X-C motif chemokine receptor 4 (CXCR4) in the early stage of HIV infection." (PMID 36539633, 2023). "Due to the capability of HIV to develop resistance by switching from CCR5 to CXCR4, dual co-receptor antagonists could represent the next generation of AIDS prophylaxis drugs." (PMID 30717348, 2019). "This could explain the association of the early appearance of CXCR4-tropic virus with enhanced CD4+ cell depletion and progression to AIDS." (PMID 30761146, 2019). "The interaction of Nef with CXCR4 may contribute to T-cell depletion and the immune dysfunction that characterizes AIDS." (PMID 29682200, 2018). "Furthermore, the HI-Virus infects T-cells through binding to CXCR4 resulting in immunodeficiency and AIDS." (PMID 27812115, 2016). "However, in approximately 40% of subtype B HIV-1 (B-HIV) infections, viruses that utilize CXCR4 (R5X4 and X4 viruses) emerge, which is associated with rapid CD4+ T-cell decline and onset of acquired immunodeficiency syndrome (AIDS)." (PMID 25313689, 2014). "Moreover, expansion or switch to CXCR4 was observed in ~50% of R5 SHIVSF162P3N-infected AIDS macaques, with viruses that can function with both coreceptors serving as intermediates." (PMID 23369442, 2013). "Such cross-talk between CB2R and CXCR4 may have implications for AIDS patients who take cannabinoid-derived agents for therapeutic purposes." (PMID 22448282, 2012). "HIV populations are predominantly CCR5-using at the start of infection and switch to being CXCR4-using in roughly 50% of HIV subtype B infections before progressing to AIDS; this proportion varies substantially among HIV subtypes with the highest reported in subtype D." (PMID 23133358, 2012). "Recently it was demonstrated that in subtype C HIV infections the virus fails to evolve to CXCR4 usage during the later stages of the disease and most of the AIDS associated viruses in these patients utilize CCR5." (PMID 23202514, 2012). "The CB2R may be considered as an adjunct therapeutic target for inhibition of CXCR4-tropic viral spread to resting T cell populations in patients with AIDS." (PMID 22448282, 2012). "The increased number of new targets may explain the rapid decline in CD4+ T cell numbers and increased viral load in late-stage AIDS patients with CXCR4-tropic virus." (PMID 22448282, 2012). "R5 viruses with an enhanced macrophage-tropism were isolated from adult and pediatric AIDS patients who did not develop CXCR4-using variants." (PMID 22420378, 2012). "Viruses using the CXCR4 coreceptor emerged during the course of infection; and were detectable in 21 out of 43 (49%) children analyzed after 84 months of age and in the majority of late AIDS (8 of 13 analyzed cases; 62%)." (PMID 22962615, 2012). "Use of CXCR4 antagonists combined with CCR5 antagonists/fusion inhibitors might lead to a useful candidate for clinical AIDS chemotherapy." (PMID 19787093, 2008). "CXCR4 is also known to be the receptor for viral ligands, such as viral Macrophage Inflammatory Protein-II (vMIP-II) encoded by Kaposi’s sarcoma-associated herpes virus and the surface subunit (gp120) of the envelope glycoprotein of X4 strains of HIV-1, the etiologic agent of AIDS." (PMID 36770826, 2023).
AIDS (continued). "In addition, it may be related to the fact that the proportion of co-receptor CXCR4 of CD4 + T cells in AIDS patients infected with CRF01_AE is significantly higher than those observed in patients infected with other subtypes." (PMID 36539633, 2023). "However, during the course of infection, the co-receptor usage preference of HIV-1 shifts from CCR5 to CXCR4 in 50% of the infected individuals, a change that is frequently associated with the accelerated CD4+ T-cell decline and the rapid progression toward AIDS." (PMID 24312095, 2013). "Human immunodeficiency virus type 1 (HIV-1), the causative agent of acquired immunodeficiency syndrome (AIDS) in humans, infects CD4+ T cells as well as macrophages and dendritic cells by binding to its primary receptor, CD4, and a co-receptor, usually CCR5 or CXCR4." (PMID 23301078, 2013). "However, the presence of CXCR4-using variants is not an obligatory prerequisite for disease progression and a significant proportion of individuals progress to AIDS and AIDS-related death while harboring exclusively R5 HIV-1 variants." (PMID 21284904, 2011). "Notably, the time from seroconversion to AIDS is not significantly different between individuals who harbor only R5 variants as compared to individuals with detectable CXCR4-using variants." (PMID 21284904, 2011). "Thus, AIDS and death presumably occurs in the absence of CXCR4-using variants for a substantial number of HIV+ patients and is caused directly by R5 viruses." (PMID 18205925, 2008). "Interestingly, in the HSPC model employed here, the dominant expression of the CXCR4 coreceptor over the CCR5 coreceptor suggests that hematopoietic progenitors may be preferentially infected by CXCR4-tropic HIV, which is linked to disease progression and immune failure in HIV/AIDS." (PMID 39354676, 2025). "Our previous research has shown that within this cohort, HIV-2 replication rates were increased in people who progress to AIDS as compared with ECs, and replication rates also increase with the switch from CCR5 to CXCR4." (PMID 40599486, 2025). "Nevertheless, HIV-1 viruses using the CCR5 co-receptor, characteristic of the early stages of infection, do not downmodulate CD4, differently from viruses entering through CXCR4 or CXCR4/CCR5, which are common during AIDS." (PMID 38787201, 2024). "In comparison, the long-term infected and AIDS participants displayed both CCR5 and CXCR4-tropic strains." (PMID 38420260, 2023). "Chemokine receptors, such as CXCR3, CXCR4, CCR5, and CCR7, play a critical role in many infectious diseases, including AIDS and TB." (PMID 35712309, 2022). "For each patient, PBMCs were collected early after the appearance of CXCR4-using viruses (mean CD4TL count = 438/μl) and at the time of AIDS (late) (62 CD4TL/μl)." (PMID 33872329, 2021). "CXCR4-using viruses are thought to accelerate depletion of CD4 T lymphocytes (CD4TL) and AIDS development." (PMID 33872329, 2021). "Host genes collectively known as AIDS restriction genes (ARGs); C-C type chemokine receptor 5 (CCR5) and C-X-C chemokine receptor type 4 (CXCR4) have been known to modify individual response to HIV-1 exposure, infection and pathogenesis markedly." (PMID 31900106, 2020). "Chemokine receptors CCR5 and CXCR4 are considered the main coreceptors for initial HIV infection, replication and transmission, and subsequent AIDS progression." (PMID 29560468, 2018). "It is assumed that the acquisition of CXCR4-usage is a key event in the progression to human AIDS; however, our FIV studies caution against such interpretations, because all FIVs utilise CXCR4 as the sole co-receptor for infection." (PMID 29056666, 2017). "Such investigations are of importance, as the use of the CXCR4 co-receptor is correlated with late HIV infection and AIDS." (PMID 26629902, 2015). "Considering the widespread expression of CXCR4 and other chemokine receptors in the nervous system, CXCR4 is an important factor in the neuro-pathogenesis of HIV/AIDS." (PMID 24403874, 2013).
AIDS (continued). "Since our results suggest that the rs1801157 GA genotype is associated with a higher risk for developing AIDS, and that this effect is linked to the presence of viral strains using CXCR4, these patients may not be ideal candidates for a CCR5 inhibitor-based therapeutic regimens." (PMID 22962615, 2012). "Patients progressing to AIDS often harbor viral populations that can use multiple coreceptors including CCR5, CXCR4 and one or more minor coreceptors." (PMID 21284904, 2011). "The B1 V3 (7a V3) is from an AIDS patient, more positively charged (recombinant ID of B1) and rendered HIV-1 neutralization-sensitive and CXCR4-tropic." (PMID 18787705, 2008). "Given the progressive emergence of X4 viruses in the course of AIDS disease even under HAART, the availability of a potent CXCR4 antagonist as part of salvage therapy is of utmost interest." (PMID 18377645, 2008). "Although CXCR4 expression on CD4+ T cells does not vary during AIDS, CCR5 expression is increased compared to HIV-infected non-AIDS individuals." (PMID 38420260, 2023). "As AIDS progresses, there is a shift in viral coreceptor use from CCR5 to CXCR4." (PMID 36443691, 2022). "The low frequency of CXCR4 use was not surprising as virus CXCR4 use has previously only been reported from HIV-2 infected individuals with clinical symptoms of AIDS or low CD4+ T-cell counts." (PMID 36366545, 2022). "An alternative explanation for LoC could be a switch in the viral tropism from CCR5 to CXCR4, which has been described to precede a decrease in CD4 T-cell counts and progression to AIDS (37, –, 40)." (PMID 30487276, 2019). "We previously reported that the full length Nef protein and Nef peptides containing residues 50–60 (herein referred to as motif 1, M1) bind to CXCR4 and initiate the apoptotic program in CD4+ T cells which may contribute to the pathogenesis of AIDS in vivo." (PMID 29682200, 2018). "Moreover, CXCR4 is known to be a major receptor for the human immunodeficiency virus-1 (HIV-1) upon infecting human T-cells leading to immunodeficiency and AIDS." (PMID 27812115, 2016). "As CXCR4 is also a coreceptor for HIV T-lymphotropic virus, enabling its intracellular penetration, agents blocking the receptor are important in the treatment of AIDS." (PMID 25866451, 2015). "CXCR4 and its ligand SDF1α are important factors in the neuropathogenesis of HIV/AIDS." (PMID 25078297, 2014). "The only non-silent CXCR4 polymorphism identified in several HIV-1 infected individuals, the CXCR4 T278C change, was not yet proven to be associated with progression to AIDS." (PMID 24167505, 2013). "Molecular clones of subtype B and subtype C R5 SHIVs that are mucosally transmissible, highly replication competent and capable of inducing AIDS in rhesus macaques have been described, but expansion or conversion to CXCR4 usage has not been observed." (PMID 23369442, 2013). "89.6 is a prototype for syncytium-forming, highly cytopathic HIV-1 viruses that replicate to high titers in cells bearing either CXCR4 or CCR5 receptors, reflective of isolates that may be found in individuals with AIDS." (PMID 23133620, 2012). "A significant fraction of patients progresses to full-blown AIDS without experiencing an overt switch to CXCR4 usage." (PMID 21284904, 2011). "AIDS-associated, CCR5-tropic (R5) HIV-1 clones, isolated from a patient that never developed CXCR4-tropic HIV-1, replicate to a greater extent and cause greater cytopathic effects than R5 HIV-1 clones isolated before the onset of AIDS." (PMID 18510766, 2008). "For the majority of HIV+ patients, AIDS and death result from replication by HIV-1 R5 viruses in the absence of detectable CXCR4-using variants." (PMID 18205925, 2008). "However, CXCR4 use was not identified from later time points in any of the four individuals, including the individual who had developed AIDS and later presented with very low T-cell levels (CD4+ T-cell count = 60 cells/μL, CD4% = 6)." (PMID 36366545, 2022).
AIDS (continued). "However, a few exceptions have been noted in which CXCR4 use emerged following experimental infection, which was associated with profound CD4+ T cell loss although not clinical AIDS." (PMID 20865163, 2010). "Notably, several inhibitors for CXCR4 have been conceptualized and developed, with AMD3100 standing out as one of the most significant achievements, having been approved by the FDA in 2008 and showing efficacy in the treatment of cancer and AIDS, as well as transplantation." (PMID 39070795, 2024). "Furthermore, the successful disruption of CXCR4 in Rhesus macaque CD4+ T cells may accelerate gene therapy studies for AIDS in non-human primate models." (PMID 26481100, 2015).